HGF (hepatocyte growth factor)
Diseases named in the same sentence as HGF in open-access papers (continued):
Sharing a sentence is not in itself a finding about the gene and the disease.
cancer (continued). "Importantly, mouse lung analysis revealed that HGF inhibition also reduced the capacity of A549 cells to metastasize to lungs in a significant manner while ectopic expression of miR-16 in CAF154-hTERT fibroblasts reduced the metastasizing potential of cancer cells, albeit not significantly." (PMID 29558956, 2018). "Cancer cell migration stimulated by conditioned medium from intermediate (SC41) and low (SC42) HGF-producing PSCs was not inhibited by TGFβ treatment of the PSCs." (PMID 29069737, 2017). "In the absence of HGF, IRCR201 displayed more potent cancer cell growth inhibition in A549 compared to huOA5D5.v2." (PMID 28902178, 2017). "Migration assays showed that HGF tended to increase cancer cell motility in MiaPaCa2(par), but INC280 did not affect either constitutive or HGF-induced motility." (PMID 25884642, 2015). "The culture supernatants of measured cancer cells (KYSE30, KYSE50, KYSE150, KYSE220, T.TN, TE-8, TE-11, TE-14, and TE-15) contained virtually no HGF or FGF7, suggesting that the autocrine activity of these cells was minimal." (PMID 25884729, 2015). "Unlike T24, 786-0 cells express both HGF and c-MET, representing a cancer early progenitor cell marker." (PMID 24797571, 2014). "In conclusion, Met expression, activation state, subcellular localization and also HGF co-receptors expression, such as CD44, have clinical relevance for novel targeted therapies in a cancer for which no effective treatment is currently available." (PMID 28548074, 2014). "In this review, we will focus mainly on immune aspects and cancer, especially as related to non-classical Nrp ligands such as TGF-β and HGF." (PMID 22948112, 2012). "Our data show that cancer cells with mutant MET (not the wild type) and MET pathway activation via exogenously added HGF have an increased proliferation, invasiveness and colony formation capacity." (PMID 21847116, 2011). "The mechanism whereby HGF activation of c-MET leads to increased motility, migration, and invasion in cancer cells has not been well-defined." (PMID 17667909, 2007). "In vitro wound-healing tests evaluating the effect of tepotinib, with or without HGF, on closure of a gap induced by scratching a layer of NCI-H441 lung cancer cells demonstrated that tepotinib inhibits cancer cell migration at clinically relevant concentrations." (PMID 36999986, 2023). "Overall, these results directly define the HGF/MET axis as a driving force of the cell-autonomous metastatic process and suggest that it enhances the malignant phenotype by boosting pro-invasive cues, even when it is not the driver of cancer growth." (PMID 37345079, 2023). "To investigate whether EpCAM and HGFR activation cooperatively regulates cancer progression and metastasis, we examined the phosphorylated ERK and AKT levels in EpCAM knockout cells with or without HGF treatment." (PMID 37543570, 2023). "In vivo, tepotinib has been shown to be able to induce tumor regression in a human-cancer mice model, irrespective of whether or not MET activation was dependent on HGF." (PMID 37373267, 2023). "While MET overexpression and activation by HGF does not warrant its designation as a pivotal CSC marker, these studies demonstrate a role played by MET signaling that enhances therapeutic resistance and stem cell maintenance in these cancers." (PMID 34055785, 2021). "HGF/c-MET inhibition (Hi, Ci or Hi + Ci) did not alter cancer cell proliferation." (PMID 32203220, 2020). "In addition, it has been demonstrated that hepatocyte growth factor (HGF) induces AXL phosphorylation, independent of GAS6, and that the Met-AXL-Elmo2-Dock180 complex is critical for HGF-induced migration of cancer cells." (PMID 31694201, 2019). "The discrepancy between the results of these studies and our data suggests that in the presence of a continuous source of HGF secretion (i.e. PSCs) as in our study, c-MET inhibition alone may not be sufficient to significantly reduce cancer progression." (PMID 29100344, 2017).
cancer (continued). "While HGF might not play an important role for hypoxia-induced EMT, HGF might stimulate EMT of cancer cells via the cancer-stromal interaction." (PMID 23690936, 2013). "We hypothesised that the ability of curcumin to downregulate HGF production from fibroblasts in the co-culture model may be responsible for the reduced invasive capacity of NSCLC cells, rather than just a direct effect of curcumin on the cancer cells per se." (PMID 31963196, 2020). "The role of the HGF/c-MET pathway in PSC-cancer cell interactions was determined by performing indirect co-culture experiments and assessing the effects of PSC secretions on cancer cell functions in the presence or absence of HGF/c-MET inhibitors and/or gemcitabine." (PMID 29100344, 2017).
infection (69 papers, 2000 to 2025). The state of being infected such as from the introduction of a foreign agent such as serum, vaccine, antigenic substance or organism. "Elevated serum HGF concentrations early in symptomatic infection and their association with ICU admission are possible indicators of an ongoing severe respiratory syndrome associated with interstitial pneumonia." (PMID 37504277, 2023). "HGF values peaked during the febrile and critical phases, and upregulation was associated with clinical signs of plasma leakage and secondary infection." (PMID 36297236, 2022). "Based on the biology of HGF, our observation of increased serum levels early in symptomatic infection and its association with ICU hospitalization is likely an indicator of an ongoing severe respiratory syndrome associated with interstitial pneumonia." (PMID 34373466, 2021). "We have studied HGF during infectious diseases and found that HGF was produced in high amounts both systemically and locally during injuries caused by infection." (PMID 15826299, 2005). "However, inhibition of c-MET led to the loss of pro-osteogenic effects in hBMSCs with rAd-HGF infection compared with DMSO-treated and rAd-HGF-infected cells." (PMID 29510550, 2018). "High levels of systemic HGF have been detected during injuries caused by infection." (PMID 26408034, 2015). "High amounts of HGF have been determined systemically during injuries caused by infection." (PMID 15826299, 2005). "As a result, the HGF-Met system stands out as both a therapeutic target and a marker for infections." (PMID 39471168, 2024). "At this point we were able to conclude that the initial values of distinct inflammatory biomarkers are good or excellent predictors for disease severity (e.g., CRP), Delta variant infection (e.g., suPAR) and mortality (e.g., LDH, sTREM-1, HGF, suPAR)." (PMID 37388734, 2023). "While hepatitis B or C virus (HBV/HCV) infection is a major cause of HCC, aberrant activation of c-Met oncogene, the receptor of hepatocyte growth factor (HGF), plays an important role in HCC initiation and progression." (PMID 37779207, 2023). "For instance, HGF levels reached 580.8 pg/mL [95% CI 327.5-1610] in the Delta moderate infection compared to 299.2 pg/mL [95% CI 195.7-625.1] in the Omicron infection." (PMID 37388734, 2023). "AAV‐HGF's infection acting time was the longest; the HGF expression peak appeared at day 11 post‐infection, while the overexpressing‐maintained time was the longest, too, about 31 days." (PMID 35922965, 2022). "Ad‐HGF's infection acting time was the shortest; the HGF expression peak appeared at day 2 post‐infection, and the overexpressing time was maintained for about 14 days." (PMID 35922965, 2022). "We showed that the onset of parasite-induced neutrophil recruitment observed from three weeks post infection correlated with increased HGF levels at the site of infection." (PMID 35041723, 2022). "In chronic infected inflammatory lesions, cutaneous damage at the site of infection induces HGF release." (PMID 35041723, 2022). "In contrast, the expression of HGF (a known marker for CHIKV recovery during acute infection) was upregulated during CMPD1 treatment thereby showing the effectiveness of CMPD1 against CHIKV in mice." (PMID 34780576, 2021). "Persistent inflammation due to infection was shown to induce higher serum HGF levels in the clinical and experimental settings." (PMID 32630328, 2020). "The maximum level of HGF was 23.6 ng/103 cells/48 h on day 11 after infection, which was 100-fold higher than the basal protein production by non-transduced cells (0.015 ng/103 cells/48 h)." (PMID 31238604, 2019). "Unexpectedly, when cells were infected with recombinant adenoviruses, inhibiting the WNT pathway significantly suppressed cell proliferation induced by rAd-HGF infection when compared with the rAd-Ctrl-infected cells treated with DMSO (p < 0.05)." (PMID 29510550, 2018).
infection (continued). "During massive liver damage induced by trauma, infection, toxin exposure, and inflammation, pro-HGF is proteolytically cleaved by HGF activator, urokinase-type plasminogen activator, matriptase, and so on, and becomes the biologically active form of HGF." (PMID 30083132, 2018). "In contrast to that in the growth medium, rAd-HGF infections led to a significant decrease in the total number of cells in osteogenic differentiation medium with mock treatments of DMSO as controls." (PMID 29510550, 2018). "In this study, the MOI-dependent effects of rAd-HGF infection for HGF expression on hBMSC proliferation and osteogenic differentiation have been explored, while the roles of c-MET-related signaling pathways are also investigated." (PMID 29510550, 2018). "In this study, the effects of multiplicity of infections (MOIs) of recombinant adenovirus carrying HGF gene (rAd-HGF) on human BMSC proliferation and osteogenic differentiation were systemically examined." (PMID 29510550, 2018). "A previous study identified dermal fibroblasts as a major source of HGF in skin upon infection or stimulation with pro-inflammatory cytokines indicating a role for HGF/Met signaling also in dermal tissue homeostasis." (PMID 29616031, 2018). "Although there was some elevation in cell amounts resulting from infection with rAd-HGF compared with rAd-Ctrl at MOI = 50, such a significant difference disappeared beginning at five days post infection." (PMID 29510550, 2018). "The results in DMSO-treated cells clearly indicated that the pro-osteogenic effects induced by rAd-HGF infection were significantly enhanced compared with that of rAd-Ctrl-infected cells (p < 0.01)." (PMID 29510550, 2018). "Given that HGF has been shown to facilitate liver stage infection, we investigated the cellular source of HGF in infected livers." (PMID 28220125, 2017). "To untangle the effect of HGF in Plasmodium liver stage infection, we pre-treated hepatocyte primary cultures of C57BL/6 and BALB/c mice with HGF 1 h prior infection and observed that HGF conditioning similarly impairs parasite yield in both mouse strains." (PMID 28220125, 2017). "Altogether, these results strongly suggest that HGF is secreted by Kupffer cells and acts in an endocrine fashion to reduce successful progression of infection in parasitized hepatocytes." (PMID 28220125, 2017). "In contrast, gene expression of antifibrogenic factor (hepatocyte growth factor) was significantly higher in C5aR1-/- mice than in WT mice at day 2 and day 14 after infection." (PMID 27370410, 2016). "In bacterial meningitis, pneumonia and acute bacterial gasteroenteritis, there is local production of HGF at the site of infection." (PMID 26408034, 2015). "Levels of HGF assessed by ELISA increased approximately 15-fold in Dppi-/- and Dppi+/+ mice after infection compared to baseline in uninfected Dppi+/+ mice." (PMID 25938594, 2015). "It is clear that HGF protein level obviously increased after infection with Ad-HGF than hUC-MSC cells alone at different time-point (**P < 0.01)." (PMID 25276829, 2014). "Since regulation and execution of HGF signalling is dependent on phosphorylation of c-Met, this was investigated in VSMCs after AdHGF-, AdNK4- and AdEGFP-infection and quantified by densitometry using β-tubulin as a protein loading control." (PMID 21920521, 2011). "We studied the amounts of HGF in faeces of patients with infectious gastroenteritis and found that the levels of HGF were significantly elevated during infection." (PMID 15826299, 2005). "At the time of infection, the immune response produces pro-inflammatory cytokines that stimulate stromal cells to produce pro-hepatocyte growth factor (pro-HGF) and eventually is activated into hepatocyte growth factor (HGF), which helps the coagulation process in endothelial and epithelial cells." (PMID 37504277, 2023).
infection (continued). "Moreover, we demonstrated that mechanisms responsible for BsAb-5 in CD166+ LCSCs included inducing c-MET degradation and inhibition of HGF-stimulated c-MET-Notch pathway by using AdHGF infection, nuclei location, and Western blot assays." (PMID 29187584, 2019). "Treatment with LY294002 could greatly suppress the level of hBMSC osteogenesis elevated by rAd-HGF infection." (PMID 29510550, 2018). "However, the enhanced cell proliferation became more significant starting from the second day after higher MOIs (MOI = 250 or 1250) of rAd-HGF infection, which is probably owing to the higher HGF expression induced by rAd-HGF infection with the higher MOIs." (PMID 29510550, 2018). "However, at the same time, inhibiting c-MET eliminated the promotive effects of rAd-HGF infection on hBMSC osteogenesis, indicating that c-MET also contributed to hBMSC differentiation." (PMID 29510550, 2018). "In contrast, significant increase in HGF secretion compared with the rAd-Ctrl infection group could be observed in higher MOI (MOI = 50) of rAd-HGF infection (p < 0.05)." (PMID 29510550, 2018). "For this goal, the WNT inhibitor, Wnt-C59, was used to treat cells before rAd-HGF infection." (PMID 29510550, 2018). "In addition, we found that reduction of parasite burden by HGF was attributable to a significant decrease in the number of hepatocytes carrying EEFs, detectable from 24 h post-infection onward." (PMID 28220125, 2017). "After in vivo infection, HGF is upregulated in the liver and is mainly expressed by Kupffer cells." (PMID 28220125, 2017). "However, our data imply that HGF also has a role in controlling infection by inducing apoptosis of parasitized hepatocytes through a mechanism that transcends Plasmodium species and does not require parasite traversing." (PMID 28220125, 2017). "Effective antibiotic therapy reduces systemic HGF levels during infection." (PMID 26408034, 2015). "The infection efficiency of Ad-HGF reached 99.64 % in hDPSCs when the MOI was 150:1." (PMID 26670567, 2015). "Thus, we overexpressed HGF in the second passage of cultured neonatal rat CFs by infection with AdHGF." (PMID 24840640, 2014). "However, the expression of HGF, was upregulated in the myocardium after infection and we observed a 2-fold increase after injection of MSCs (p = 0.036 vs. PBS-CVB3) but not after administration of cardiac fibroblasts." (PMID 22815907, 2012). "However, 8 days after AdHGF infection of VSMCs, Notch3 was mainly localised in the nuclei, suggesting HGF over-expression triggers Notch3 activation." (PMID 21920521, 2011). "Specifically, we found that this augmented re-epithelialization of wounded keratinocytes was linked to the production of HGF by EDK cells, as the diminished production of this growth factor upon shRNA infection significantly decreased tissue re-epithelialization." (PMID 21338517, 2011). "The protein expression of seven proteins (CD8A, ST1A1, AXIN1, FGF-5, MMP-10, HGF, SIRT2) was significantly decreased and the protein expression of two proteins (MMP-1, TNFRSF9) was significantly increased in caspase-1-deficient cells compared to Cas9 cells following HK1651 infection." (PMID 40137780, 2025). "The significantly elevated expression of HGF, IL-1R1, and IL-6RA in female mice in group ET-EECP might be associated with limited pro-inflammatory effects and would be helpful in the clearance of infection caused by alcohol in the liver tissue." (PMID 31998465, 2019). "On the other hand, a recent report highlighted that hepatocyte growth factor (HGF) from KCs of infected mice is essential in promoting apoptosis of Plasmodium-infected hepatocytes, suggesting that the KCs do produce soluble molecules to affect the overall state of the liver during the infection." (PMID 30477234, 2018). "However, rAd-HGF infection could inhibit these two pathways to suppress hBMSC proliferation under this condition." (PMID 29510550, 2018).